ENSG00000284512 (novel protein)
Gene: Protein-coding gene on chromosome 16 (81,022,316 to 81,096,284, reverse strand). Ensembl gene ENSG00000284512.
Genetic constraint (gnomAD): Loss-of-function variants: 1 observed, 2.77 expected, observed/expected ratio (o/e) 0.36, 90% interval 0.12 to 1.54. That is too few expected variants to judge how well the gene tolerates losing a copy. Missense variants: 56 observed, 37.47 expected, observed/expected ratio (o/e) 1.49, 90% interval 1.2 to 1.84. Synonymous variants: 22 observed, 14.72 expected, observed/expected ratio (o/e) 1.49, 90% interval 1.05 to 1.91.